MKI67 (marker of proliferation Ki-67)
Diseases named in the same sentence as MKI67 in open-access papers (continued):
Sharing a sentence is not in itself a finding about the gene and the disease.
cancer (continued). "Next, the expression of all cortical cytoskeleton genes in the cancer tissues was compared to that of MKI67, encoding the well established marker of cell proliferation in cancer, Ki67." (PMID 20860828, 2010). "The common signature at relapse also unveils several genes already described in the death-from-cancer signature including MKI67, KNTC2 (HEC1) and BUB1B." (PMID 20885975, 2010). "However, the applicability of MKI67 against certain cancer types was obscure due to different regulatory roles, different prognosis values, and varied cutoff values of MKI67 in diverse cancer types." (PMID 40070823, 2025). "The diverse functions of MKI67 expression may partially explicate MKI67 carried out an opposing impact on the prognosis of different cancer types." (PMID 40070823, 2025). "MKI67 expression was significantly upregulated across varied cancer types verified by datasets." (PMID 40070823, 2025). "By RT–qPCR, we observed that all cancer cells co-cultured with CRISPRa-treated adipocytes had significantly reduced levels of the proliferation marker MKI67 (other than Panc 10.05 and DU-145 treated with PRDM16 CRISPRa) compared to control cells, with UCP1-CRISPRa having the greatest effect." (PMID 39905264, 2025). "Above all, the results revealed that MKI67 expression plays diverse functions in different cancer types, which may partially explain MKI67 performed an opposing impact against the prognosis of various cancer types." (PMID 40070823, 2025). "For instance, MKI67 expression remains constant in cancer cells without evident mutations, but variations in transcription patterns during the S phase have been observed across different cell lines." (PMID 40492213, 2025). "Notably, MKI67 expression have different effect on diverse cancer types, such as positively related to Macrophage M1 cells in BLCA, BRCA, KIRC, LUAD, and THCA; negatively related to Macrophage M1 cells in CESC, GBM, LUSC, READ, TGCT, and THYM." (PMID 40070823, 2025). "MKI67 and S100B are low-specificity biomarkers used in several cancer types." (PMID 40004203, 2025). "Taken together, there was a close association between the high MKI67 expression and certain clinicopathological features and clinical parameters, such as poor differentiation, TNM classification, and clinical stage, among different cancer types." (PMID 40070823, 2025). "MKI67, a cell proliferation marker, is upregulated in cancer." (PMID 39354287, 2025). "Overall, MKI67 expression was significantly upregulated across varied cancer types." (PMID 40070823, 2025). "We integrated analyzed the function of P4HA3 among 33 types of cancers, and found that P4HA3 was associated with proliferation markers (PCNA and MKI67), EMT markers (VIM, TWIST1, SNAI1, SNAI2, FN1 and CDH2), extracellular matrix (ECM) markers (MMP9, MMP7, MMP2 and MMP14)." (PMID 39504328, 2024). "This suggests that MKi67 could be an important biomarker for cancer progression and therapeutic outcomes." (PMID 38674285, 2024). "Gene MKI67 has been treated as a candidate prognostic prediction for cancer proliferation." (PMID 38741183, 2024). "The 8 cell types were annotated based on the differentially expressed markers: Bnip3 for autophagic cancer cells, Mki67 for proliferating cancer cells, Cd14, Apoe, C1qc, Mrc1, Lyz2 for monocytes, Col3a1 for fibroblasts, Cd3e and Gzma for T cells, Flt1 for endothelial cells, and Klk1 for DCs." (PMID 38802348, 2024). "Additionally, we confirmed that Mki67 gene expression in cancer cells was increased in the DTX-treated tumors relative to vehicle treated control concurring our flow cytometry data." (PMID 37699010, 2023).
cancer (continued). "Several of the top SNPs are in genes associated with PCa or PCa processes, including MKI67 (rs8473), PCSK6 (rs80278342), ABCB6 (rs60322991), and TCHP (rs11068997); or other cancer-associated processes, including GGA2 (rs1135045), H1-5 (rs11970638), and COL15A1 (rs2075662)." (PMID 38052806, 2023). "Notably, CDK4 was highly expressed in P-Tex2 cells, cancer epithelial cells, and fibroblasts, while MKI67 was highly expressed in P-Tex1 clusters." (PMID 36811599, 2023). "In conclusion, these results suggest that MKI67 positive cancer cells may contribute to chemotherapy resistance in HGSOC." (PMID 36248860, 2022). "In clinicopathology, Ki67/MKI67 is commonly referred to as a marker of cancer cell proliferation." (PMID 36241648, 2022). "MKI67 is a cell proliferation marker that has been applied to the study of cancer." (PMID 36389368, 2022). "Further, we assessed the correlation between SKP2 and MKI67 in pan-cancer." (PMID 35685435, 2022). "Strikingly, SKP2 was positively correlated with the expression of MKI67 in almost all cancer types." (PMID 35685435, 2022). "In addition, CENPA also appears as the main regulator of MKI67 (Ki-67), a common prognostic and proliferation marker widely used in cancer histopathology." (PMID 36358698, 2022). "Finally, the 5 RNAs, including CCNA2, MKI67, KIF11, miR-30a-5p, and VPS9D1-AS1, were further identified as candidate crucial RNAs associated with cancer." (PMID 35186743, 2022). "The positive correlations of TNS3 and MKI67 were found in most cancers, including ESCC." (PMID 34047714, 2021). "Furthermore, MKI67 coexpression genes were suggested to play a significant role in the prognosis prediction of cancer." (PMID 34724892, 2021). "MKI67 acts as a prognostic prediction biomarker in several cancers, particularly LIHC." (PMID 34724892, 2021). "Plenty of evidence supports the role of MKi67 in diagnosing cancer." (PMID 34724892, 2021). "Furthermore, MKi67 has been studied extensively in retrospective articles as a candidate prognostic prediction factor for cancer proliferation." (PMID 34724892, 2021). "Furthermore, in some types of cancers, including THCA, BRCA, SKCM, KIRC, and GBM, the immune infiltration degrees were markedly associated with MKI67." (PMID 34724892, 2021). "MKI67 expression decreased in many cancers related to the dismal prognostic outcome of LIHC." (PMID 34724892, 2021). "Oncomine, GEPIA2, and HPA were adopted to analyse MKI67 levels in different types of cancers." (PMID 34724892, 2021). "CCNB1, CKS2, MKI67, RRM2, TK1 and TOP2A were found with positive clinical correlation to GLEASON SCORE, and we could clearly identify the core factors as cancer risk factors, the expression level increased as Gleason score elevated." (PMID 32266115, 2020). "Previous studies have reported the abnormally high expression of MKI67 in multiple types of cancer, including CRC, and found that MKI67 could be an independent prognostic biomarker in these types of cancer." (PMID 32127012, 2020). "Elevated MKI67 expression indicates rapid cancer progression and poor prognosis." (PMID 32348423, 2020). "Ki‐67 (MKI67) is a marker of cellular proliferation of cancer." (PMID 29511610, 2018). "We further found that ADSCs could upregulate the mRNA expression of proliferation-related genes in cancer cells, including MKI67 and PCNA." (PMID 25797257, 2015). "In this study, the controversial expression of Mki67 between Grhl2 overexpressed cancer cell lines and Grhl2 overexpressed breast epithelia cell line might be due to the difference in cell cultures or cell context-specific effects." (PMID 23441166, 2013).
cancer (continued). "Also among the genes in the attractor is MKI67 (aka Ki-67), which has been widely used as a proliferation rate marker in cancer." (PMID 23468608, 2013). "Above all, the results of TCGA database and our validation present that the high MKI67 expression was associated with certain clinicopathological features and clinical parameters, for instance, poor differentiation, TNM classification, and clinical stage, among some cancer types." (PMID 40070823, 2025). "It was found that MKI67 may have great potential as a cancer prognostic and immune infiltration marker, whereas the current study was insufficiently validated due to the lack of in-depth experiments to validate its specific immune infiltration relationship with TMEs." (PMID 40070823, 2025). "Moreover, genes that are upregulated and downregulated at both RNA and protein levels across multiple types of cancers were identified and defined as PCUGs and PCDGs, respectively, which encompass a large number of oncogenes such as MKI67, TRIP13, SMC4, UBE2C, CDK1, and TOP2A." (PMID 39884577, 2025). "Transcriptomic analysis revealed the upregulation of cell cycle- (MKI67, CCNE2 etc.)and cancer-related genes (SYK, MCM2 etc.), and GSEA confirmed the enrichment of Rb-related pathways." (PMID 41535675, 2026). "The epithelial OC origin of the PDC2 and PDC3 samples was confirmed by the expression of OC-specific markers PAX8 and CD24, epithelial makers MKI67, EPCAM, KRT8 and KRT18 and cancer stem cell markers such as CD44 and ROR1." (PMID 39482470, 2025). "In numerous in vivo and in vitro studies, a variety of cancer-related mRNAs have been identified, including PTEN, ACTB, MAPK4, MKI67, c-MYC, and CD44." (PMID 40082414, 2025). "The RCC score includes a panel of 12 genes, with 7 cancer-related genes (stromal genes: INHBA, BGN, and cell cycle genes: MKI67, MYC, MYBL2, GADD45B) and 5 reference genes, and is used to predict CRC recurrence." (PMID 40664638, 2025). "Subsequently, we selected PILRA, MKI67, and UBE2C, which were significantly upregulated in both cancer types, for further validation using immunohistochemistry." (PMID 41328437, 2025). "Genes such as TPX2, MKI67, EXO1, and CTHRC1 exhibited progressive upregulation from infection to cancer, highlighting involvement in cell cycle regulation, DNA repair, and extracellular matrix remodeling." (PMID 40445003, 2025). "Here, via multiomics analyses of 314 SCLCs, we found that the ASCL1+/MKI67+ and ASCL1+/CRIP2+ clusters accounted for 74.38% of the 190,313 SCLC cancer cells from 39 patients, with the ASCL1+SOX1+ stem-like cell cluster across SCLC subtypes." (PMID 40925909, 2025). "iPSC-astrocytes’ role in mitigating cancer cell death was further evidenced by the upregulation of extracellular signal-regulated kinase 1 (ERK1) and the proliferation marker Ki-67 (MKI67)." (PMID 40149331, 2025). "Identifying hub genes such as TPX2, MKI67, and EXO1, which are involved in cell cycle regulation and DNA repair, further supports the cancer-specific relevance of our biomarkers." (PMID 40445003, 2025). "By employing ComBat to correct for batch effects in our study and focusing on the top DEGs, we highlighted genes such as TPX2, MKI67, EXO1, and CTHRC 1, which exhibited progressive upregulation from infection to cancer." (PMID 40445003, 2025). "ln the results, METTL16 was positively correlated with the expression of MKI67 and PCNA among most types of cancer." (PMID 40015977, 2025). "Among these, PILRA, MKI67, and UBE2C showed consistently elevated expression in both cancers and were validated through RT-qPCR and immunohistochemistry, suggesting their potential as therapeutic targets." (PMID 41328437, 2025). "In BC tissues, TAP1, PILRA, UBE2C, TMEM51, and MKI67 were significantly upregulated, while the expression levels of SPP1 and CENPF remained unchanged between cancer and adjacent tissues." (PMID 41328437, 2025).
cancer (continued). "The focused heatmap of the top 10 DEGs highlighted genes such as TPX2, MKI67, EXO1, and CTHRC1, which showed progressive upregulation from infection to cancer." (PMID 40445003, 2025). "Generally speaking, Ki67 (also known as MKI67, MIB-1, PPP1R105) is a very important biomarker for the proliferation index of cancers." (PMID 38370368, 2024). "Through this analysis, we identified eight major cell types, namely B cell (CD79A), cancer cell (KRT5), cycling cell (MKI67), endothelial cell (VWF), fibroblast (COL1A1), mast cell (KIT), monocyte/macrophage (CD14) and T cell (CD3D)." (PMID 38279519, 2024). "The outcomes showed that in the majority of cancer cases, LIPT2 expression was eminently positively correlated with MKI67, PCNA, BCL2, BAX, and EPCAM, while showing a significant negative correlation with VIM." (PMID 38129565, 2023). "The results showed that CCNA2, CDK1, KIF11, MKI67, and PLK1 were significantly and positively correlated with CEP55 in pan-cancer." (PMID 37887301, 2023). "Further, we tried to collect the statistical power of the pan-cancer technique on large numbers of clinical samples to reveal the relationship between YAP1 and MKI67 using TIMER." (PMID 35685435, 2022). "As Ki67 was a vital important proliferation indicator in the cell cycle, we assessed the relationship between SKP2 and MKI67 mRNA in pan-cancer using TIMER database." (PMID 35685435, 2022). "The correlation heatmap showed the top five genes (CCNA2, CKAP2L, KIF11, MKI67 and PLK1) that were positively and significantly related to RRM2 in almost all TCGA cancers." (PMID 35740608, 2022). "Involved genes (CCNA2, MKI67, and KIF11) were found with abundant expression levels in many tissues, and they showed a significantly upregulated expression pattern in many cancer types." (PMID 35186743, 2022). "It has been reported that CD44, MKI67 and TYMS are overexpressed in many cancer types, including DTC, and regulate glucose metabolism by targeting different genes." (PMID 35528004, 2022). "The cancer genes are composed of genes that code for HER2 (HER2 and GRB7), oestrogen genes (ER, PGR, BCL2, and SCUBE2), proliferation genes (MKI67, STK15, BIRC5, CCNB1, and MYBL2), and invasion genes (MMP11 and CTSL2) as well as GSTM1, CD68, and BAG1." (PMID 36042999, 2022). "These genes include known and novel FOXL2 targets (TGFB2, SMARCA4, HSPG2, MKI67, NFKBIA) and are enriched for neoplastic pathways (Proteoglycans in Cancer, Chromatin remodeling, Apoptosis, Tissue Morphogenesis, Tyrosine Kinase Receptors)." (PMID 33639972, 2021). "Within community 2, we also identified increased expression of regulators of cell proliferation (CENPE, MKI67, TOP2A, UBE2C, guanine), cancer, and pluripotency (DNMT3B, DPPA4, MYC, POU5F1, CRABP2)." (PMID 33771987, 2021). "Cluster 4 showed high expression of cell cycle‐related genes for markers such as PCNA, MCM5, MKI67, STMN1, and CDK1, probably owing to the immune response to cancer neo‐epitopes." (PMID 33513276, 2021). "In agreement, after normalization to the canonical cell proliferation marker MKI67, the FOXM1/RHNO1 expression ratio was similar in normal and cancer tissues." (PMID 33890574, 2021). "Our recent large-scale tissue analysis demonstrated that the Ki-67 gene (MKI67) and FAM72 paralogs are co-expressed in proliferating cells in NSCs and also outside neuronal tissue (i.e., in cancer cells across various tissues)." (PMID 33804473, 2021).
cancer (continued). "Cluster 3 was highlighted by the significantly increased transcripts of proliferating marker genes, including MKI67, PCNA and DNA Topoisomerase gene, TOP2A, suggesting activated cell proliferation in this cancer cell cluster." (PMID 34055623, 2021). "Several of them were involved synthetically lethal genetic interactions, especially for RECQL4, TOP2A, MKI67 and ASPM, indicating their potential roles in drug design and cancer treatment." (PMID 32040444, 2020). "And most of the 24 DEPs (CDK1, SFN, PRKAR2B, MKI67 and MDK involved in the cell cycle; LOXL2, P4HA1, P4HA2, SPRX, DES, PRPH and CALML3 involved in construction and regulation of extracellular matrix; IL33 and EHD3 may involve in immune) were linked to cancer hallmarks." (PMID 33200655, 2020). "In the pan-cancer analysis, DEPTH scores had a significant positive correlation with MKI67 expression levels (p = 4.16 × 10−127, ρ = 0.25)." (PMID 32917965, 2020). "Normalization of DNMTs and UHRF1 to other markers of cancer cell proliferation, including PLK1 and BUB1, provided similar results as seen with MKI67 normalization." (PMID 32213861, 2020). "Considering cell cycle process is tightly correlated with cancer cell proliferation, we investigated the correlation between CCPRS and MKI67 expression." (PMID 32370292, 2020). "Of the 10 proteins, the preceding text showed that some studies identified RRM2, PLOD2, MKI67, MCM5, and CKD1 promoted cancer progression and FBP1, FBP2, ENO3, GPD1, and ASS1 inhibited cancer progression, which was consistent with our results." (PMID 33200655, 2020). "In total, 32 cancer related genes including CCND1, MKI67, HIF1A, CDH1, RRM2, and FOXM1 were subsequently identified through Ingenuity Pathway Analysis." (PMID 32348423, 2020). "The results showed that the expression of HNRNPA2B1 was significantly positively correlated with the expressions of MKI67 and PCNA, which were the classic biomarkers of proliferative cancer cells." (PMID 33134163, 2020). "To examine the link between MELK and cell division in cancer, we compared the levels of MELK expression with five well-characterized proliferation markers: MKI67, PCNA, CCNB1, MCM2, and TOP2A." (PMID 29417930, 2018). "The products of hub PCGs mainly function as protein binding molecule and were involved in important biological processes and signaling pathways in cancer (CDK1, MKI67, CENPF, COL4A6, DACH1, etc.)." (PMID 30026672, 2018). "We also found that IL-6 neutralization markedly diminished the up-regulation of MKI67 (4T1, 1.21 ± 0.22; CT26, 1.27 ± 0.31) and PCNA (4T1, 1.54 ± 0.9; CT26, 1.20 ± 0.46) induced by ADSCs in cancer cells." (PMID 25797257, 2015). "Notably, genes like fatty acid binding protein 5 (FABP5), enolase 1 (ENO1), phosphoglycerate kinase 1 (PGK1), and marker of proliferation Ki-67 (MKI67), which have been extensively studied in cancer biology, were included." (PMID 41328179, 2026). "All five cancer organoid cases co-cultured with UCP1-CRISPRa had significantly lower proliferation marker MKI67 expression compared to the negative control." (PMID 39905264, 2025). "ADCY5 expression was negatively related to proliferation marker MKi67 (P < 0.001) and invasion markers VIM (P < 0.001), implying ADCY5 may influence cancer cell proliferation and invasion." (PMID 39319137, 2024). "We identified recognized cancer driver genes (EGFR, MTOR, CCND1, and MYC) within Epi_C1_SPARC and Epi_C6_TCIM subclusters, observing high variability of CNVs in cell proliferation-related genes (TOP2A, MKI67)." (PMID 38720887, 2024). "As the molecular mechanisms involved have been uncovered gradually, increasing numbers of informative biomarkers have been identified to evaluate the degree of malignancy of various cancers, including proliferating cell nuclear antigen (PCNA) and marker of proliferation Ki-67 (MKi67)." (PMID 36133906, 2022).